RNF43 (ring finger protein 43)
Diseases named in the same sentence as RNF43 in open-access papers (continued):
Sharing a sentence is not in itself a finding about the gene and the disease.
gastric cancer (continued). "RNF43 has been reportedly expressed in both the cytoplasm and nucleus of gastric cancer cells, the cytoplasm of gastric cancer and glioma cells as well as in the nuclear membrane and endoplasmic reticulum of cervical cancer cells." (PMID 27661107, 2016). "Moreover, they also speculate that stomach cancer also harbors frequent mutations in RNF43." (PMID 27556693, 2016). "It has been found that RNF43 depletion can impair the sensitivity to γ-radiation and chemotherapy by suppressing the activation of DNA damage response via directly targeting phosphorylated H2A histone family member X (γH2AX) in gastric cancer." (PMID 37848933, 2023). "RNF43 is a negative regulator of Wnt signaling, and mutation of RNF43 is frequently found in CRC and endometrial cancers, gastric cancer, neoplastic cysts of the pancreas including intraductal papillary mucinous neoplasms (IPMNs) and mucinous cystic neoplasms (MCNs)." (PMID 34488905, 2021). "Around 18% of gastric cancers have mutations in APC and RNF43 as the primary cause of the disease." (PMID 34552611, 2021). "Moreover, RNF43 and CREBBP mutations have been frequently observed in MSI-H gastric cancer or colorectal cancer, indicating a favorable immune context in these tumors." (PMID 33947957, 2021). "In addition, we found RNF43 and PWWP2B mutations in 7 and 6 of 34 gastric cancer patients, respectively." (PMID 34149925, 2021). "We found that gastric cancer recurrence patients showed downregulated RNF43 and PWWP2B (100%)." (PMID 34149925, 2021). "Additionally, RNF43 inhibits gastric cancer stem-like cells by inactivating Wnt/β-catenin signaling." (PMID 37304674, 2021). "Accordingly, adenovirus-induced overexpression of RNF43 in gastric cancer cells reduces Wnt signaling and leads to a significant decrease in stem cell properties and tumorigenicity, further pointing towards a significant involvement of R-spondin in gastric carcinogenesis." (PMID 31248166, 2019). "Furthermore, colorectal cancer research revealed that a combination of peptide vaccines and anti-cancer drugs induced upregulation of the Wnt-inhibitor RNF43, and this therapeutic scheme has been proposed for use in patients with gastric carcinomas, too." (PMID 31248166, 2019). "Our findings indicated that RNF43 might not only participate in gastric cancer progression, but also attenuate the stemness of gastric cancer stem-like cells through the Wnt/β-catenin pathway." (PMID 28446252, 2017). "Furthermore, loss of RNF43 function promotes mouse gastric epithelium proliferation and human gastric cancer cell xenograft growth, without detectable impact on WNT signaling activity." (PMID 38260423, 2024). "Finally, highly recurrent mutations in MSI tumors, such as those affecting RNF43 and BRAF in gastric cancers were associated with high number of clonal and subclonal mutations, consistent with MSI tumors having a higher mutational load than micro-satellite stable tumors." (PMID 30212491, 2018). "Our previous study indicated that RNF43 might be a tumor suppressor protein in gastric cancer." (PMID 28446252, 2017). "Our data demonstrated that RNF43 and PWWP2B are a biomarker that predict recurrence of gastric cancer." (PMID 34149925, 2021). "In this study, we applied an RNA sequencing (RNA-seq) approach to identify RNF43 (i.e., verify a known marker) and PWWP2B (i.e., explore a novel marker) genes differentially expressed in gastric cancer and adjacent normal tissues from 34 patients." (PMID 34149925, 2021). "The RNF43 and PWWP2B genes are potential biomarkers candidates for patients with advanced gastric cancer." (PMID 34149925, 2021). "RNA sequencing data reveals that RNF43 and PWWP2B expression were down-regulated in recurrence gastric cancer patients." (PMID 34149925, 2021). "RNF43 and PWWP2B genes were weakly expressed in MKN45 cells compared with the other gastric cancer cell types." (PMID 34149925, 2021).
gastric cancer (continued). "In summary, the results of this study indicate that RNF43 and PWWP2B are downregulation in gastric cancers compared with normal adjacent gastric mucosa." (PMID 34149925, 2021). "Next, we investigated the anti-cancer effects of selected drugs in RNF43 and PWWP2B down-regulated MKN45 gastric cancer cells and xenograft model." (PMID 34149925, 2021). "Along these lines, a recent report demonstrates a non-WNT role for RNF43 in DNA-damage response in gastric cancer cells." (PMID 35039505, 2022). "As far as we know, the RNF43 gene is well known to be associated with gastric cancer, but the PWWP2B gene has not been found to be associated with gastric cancer." (PMID 34149925, 2021). "Especially, PWWP2B KO cell line formed colonies much larger than WT and RNF43 KO cells, suggesting that the PWWP2B KO might endow gastric cancer cells with accelerated proliferative capability." (PMID 34149925, 2021). "Therefore, anti-cancer effects of selected drugs were re-tested in RNF43 and PWWP2B down-regulated MKN45 gastric cancer xenograft model." (PMID 34149925, 2021). "Therefore, in this study, 1,449 FDA-approved drugs were screened to determine whether they could be used as therapeutic agents for the treatment of gastric cancer using growth inhibition assays of HAP1, HAP1 RNF43 KO, and HAP1 PWWP2B KO cells." (PMID 34149925, 2021). "Notably, reduced RNF43 function is a negative prognosis factor in gastric cancer patients and RNF43 loss-of-function type of mutation exacerbated Helicobacter pylori-induced gastric tumor carcinogenesis associated with the upregulation of WNT5A mRNA level." (PMID 34702444, 2021).
colon cancer (29 papers, 2014 to 2025). "Overall, two main hot spots were assigned as hallmarks of RNF43 mutations in colon cancer, namely, the R117 frame shift (fs), affecting the N-terminal region of the protein, and the G659fs truncation mutation, affecting the C-terminal domain." (PMID 39125653, 2024). "This is consistent with prior observations, also in colon cancer, where RNF43 was identified as a tumor-associated antigen that can elicit tumor-reactive cytotoxic T-cell responses." (PMID 35798829, 2022). "Intriguingly, we found that a colon cancer cell line with RNF43-G659Vfs*41 and BRAF-V600E mutations was sensitive to activation of Wnt signaling in vitro." (PMID 31811196, 2019). "A colon cancer cell line with RNF43-G659Vfs*41 and BRAF-V600E mutations had low levels of Wnt signaling and was inhibited by activation of Wnt signaling." (PMID 31811196, 2019). "We then asked how ZNRF3 was related to RNF43 in expression and mutation status in colon cancer as both genes are targets as well as negative regulators of Wnt signaling." (PMID 31811196, 2019). "A colon cancer cell line with RNF43-G659Vfs*41 and BRAF-V600E mutations was sensitive to activation of Wnt/β-catenin signaling." (PMID 31811196, 2019). "Further immunological studies and a role of RNF43 mutation and translocations/overexpression of R-spondin in the progression of colon cancer is planned, to explore valid biomarkers that predict clinical efficacy of immune therapy." (PMID 29293510, 2018). "They account for 41.7%~48.0% and 8.3%~12.0% of RNF43 mutations identified in colon cancer and endometrial cancer." (PMID 27338477, 2016). "RNF43 encodes the ring finger protein 43 that is involved in cell growth, and is upregulated in human colon cancer." (PMID 27461012, 2016). "Furthermore, colitis‐associated colon tumor development was accelerated in Rnf43−/− mice, and in vivo screening using the Sleeping Beauty transposon identified Rnf43 as a candidate driver of intestinal tumorigenesis." (PMID 35040131, 2022). "However, only 5.5% of colon cancers have mutations both in APC and RNF43, suggesting a differential mechanism of optimal activation of Wnt signaling in gastric and colon cancers for tumor growth and progression." (PMID 34552611, 2021). "In colon cancer, RNF43 mutations were largely exclusive with APC mutation." (PMID 31811196, 2019). "Furthermore, in colon cancer, RNF43-G659Vfs*41 mutation is most frequently associated with BRAF-V600E mutation and low Wnt/β-catenin signaling." (PMID 31811196, 2019). "Here, we used aggressive colon cancer patient-derived organoids (PDO) with co-occurring mutations in BRAF (V600E) and RNF43 (P441fs)." (PMID 40687798, 2025). "The same study also identified a mutually exclusive relationship between mutations in RNF43 and APC in CRC patients, suggesting an activating role of truncating mutations in RNF43 in the WNT pathway of colon tumours." (PMID 37048063, 2023). "N-terminal mutations of Rnf43, one of the most commonly mutated genes in CRC, have also been linked with enhanced Wnt/β-catenin signaling activity in colon cancer while C-terminal truncation mutants act similarly to the wild-type Rnf43." (PMID 33585487, 2021). "Colon tumors with RNF43-G659Vfs*41 had low Wnt/β-catenin signaling and were frequently mutated in BRAF." (PMID 31811196, 2019). "The results showed that the expression of RNF43 was decreased compared with adjacent normal tissues in colon cancer, while in lung and ovarian cancer the expression in cancer tissues and normal tissues did not exhibit a significant difference." (PMID 28446252, 2017).
colon cancer (continued). "In just one year after the initial discovery of RNF43 mutations in IPMN and MCN, recurrent RSPO2 and RSPO3 translocations were identified in 3.0% and 8.0% of colon cancer, respectively." (PMID 27338477, 2016). "An analysis investigating inactivating mutations of RNF43 that confer Wnt dependency in pancreatic ductal adenocarcinoma suggests that BRAF, ARID1A, RNF43, and KM2B mutations exhibit the highest frequency in microsatellite instability (MSI) colon cancer." (PMID 38886806, 2024). "Although future precise manipulation of RNF43 in more relevant cell models (i.e., colon cancer cell lines) are warranted, these early stage results in the HEK293T cell model have clearly shown the feasibility of programming successive point mutation and reversion using PE." (PMID 37343700, 2023). "Furthermore, USP42 stabilizes zinc and ring finger 3 (ZNRF3)/ring finger protein 43 (RNF43) on the cell surface, which plays a role in paracrine Wnt signaling in colon cancer cells." (PMID 35884607, 2022). "Various amounts of WT and mutant RNF43 plasmids were also co-transfected at 1:1 ratio into two colon cancer cell lines (DLD1 and LoVo) as well as into STF-RZ-DKO cells, and WB analysis showed that the two proteins were detected at nearly identical levels across the range of expression." (PMID 31811196, 2019). "The two recurrent fusions (ADAP1‐NOC4L and RNF43‐SUPTH1) out of five chimeras were validated in SW48 and HT29 colon cancer cell lines as well as patient tissue samples." (PMID 35702822, 2023). "In colon cancer, RNF43-G659Vfs*41 tumors showed a much lower expression of MLH1 when compared to those of RNF43-WT tumor (mean RNA-seq RSEM value of 179 vs 553, p < 0.05)." (PMID 31811196, 2019). "Ring finger protein 43 (RNF43), overexpressed in colon cancer and involved in tumor growth, was first identified using cDNA microarray profiling." (PMID 29293510, 2018). "Moreover, PAF1 knockdown decreased the expression levels of the genes such as LGR5, ID1, ID3, CD44v9, CD133, BMI1, RNF43, EPHB2, SOX9, and ASCL2, which are critical for inducing colon cancer stemness and its markers." (PMID 38182897, 2024). "Remarkably, nearly all BRAF-V600E tumors had low expression of Axin2, RNF43, and ZNRF3, but not vice versa, consistent with previous report of low Wnt signaling in colon tumors with MSI-H BRAF-V600E mutation." (PMID 31811196, 2019). "RNF43-G659Vfs*41 had been suggested to drive or facilitate colon cancer formation based on the presumption that it no longer functions in inhibiting Wnt signaling." (PMID 31811196, 2019). "In addition, other groups revealed that RNF43 expression was also elevated in adenomas of the colon, that it is down-regulated by a dominant-negative form of Tcf4 in LS174 colon cancer cells, and that expression of RNF43 was induced by Wnt3a conditioned media." (PMID 24466159, 2014). "Similarly, in two colon cancer organoids derived from the same patient (MSI subtype), only the organoid with the RNF43 G355fs mutation but not the one with the RNF43 G659fs mutation responds to the porcupine inhibitor in vitro." (PMID 27338477, 2016). "In colon cancer, WNT2 might bind to FZD3 to upregulate AXIN2, as well as RNF43 for its negative feedback regulation, in which the modification and degradation of β-catenin are key pathway events in tumor progression." (PMID 39228892, 2024).
adenoma (21 papers, 2014 to 2025). A neoplasm arising from the epithelium. "Loss of RNF43 and ZNRF3 induces rapid growth of adenomas, as RNF43 and ZNRF3 target Wnt receptors for degradation by selectively ubiquitinating Fz receptors, thereby attenuating Wnt signaling." (PMID 39329019, 2024). "Similar frameshift mutations of RNF43 were frequently found in serrated adenomas that were often accompanied by CIMP, MSI, and BRAFV600E mutations." (PMID 35040131, 2022). "In particular, MMR-D adenomas were characterized by RNF43 frameshift somatic mutations in mononucleotide repeats, frequently associated with insertions or deletions of three-repeat sequences in the APC gene." (PMID 33923068, 2021). "They detected a high frequency of RNF43 mutations and subsequently evaluated the function of RNF43, an E3 ubiquitin ligase, in organoids of serrated adenomas or mouse colon by inducing RNF43 mutations with CRISPR/Cas9." (PMID 34912798, 2021). "Interestingly, the adenomas and carcinomas of LS-298 frequently showed frameshift variants in RNF43 with high variant allele frequency (median VAF= 44.4; range = 15.69-62.3)." (PMID 38725616, 2024). "The genetic profile of colonic lesions showed that RNF43 gene mutations were frequent in both LS-associated adenomas and adenocarcinomas, while APC gene mutations, despite being detected in 40% of LS-adenomas, were more frequent in sporadic colorectal adenomas (60% of cases)." (PMID 33923068, 2021). "RNF43 mutation plays a key role as a tumorigenic driver from adenoma to carcinoma in early gastric carcinogenesis, and mutation in the tumor suppressor RNF43 and dysregulated Wnt signaling are involved in multistep gastric carcinogenesis through the adenoma-to-carcinoma sequence." (PMID 34068652, 2021). "BRAF or KRAS mutations were observed in both non-dysplastic or dysplastic sessile serrated adenomas; most MLH1-deficient sessile serrated adenomas with dysplasia displayed RNF43 mutations less frequent in sessile serrated adenomas with retained MLH1 expression." (PMID 29652830, 2018). "Frequent frameshift mutations of RNF43 are observed in LS-associated adenomas." (PMID 29652830, 2018). "We analyzed Lef1 expression in Apc-mutant tumors that are ligand independent and in Rnf43;Znrf3-mutant adenomas that are ligand dependent and have a serrated growth pattern." (PMID 34788095, 2021). "Wnt3 is not essential for ligand-independent intestinal adenomas but is essential for Rnf43;Znrf3-mutant adenomas." (PMID 34788095, 2021). "Inactivation of RNF43 and ZNRF3 induces Wnt-dependent adenoma formation, and these genes are frequently mutated in various human cancers." (PMID 32934222, 2020). "Eleven somatic mutations were located in genes involved in the early adenoma formation (APC, RNF43 and CTNNB1), whereas two mutations were detected in genes involved in later stages (ARID1A, NRAS)." (PMID 31285513, 2019). "As APC is integrally involved in the development of adenomas by both germline and somatic inactivation, RNF43 defects could promote the formation of adenomas." (PMID 38725616, 2024). "This is notable since LS colorectal tumorigenesis is generally thought to follow the classic adenoma-carcinoma sequence, whereby MMRd is a late event in adenomas, with established Wnt signaling activation due to somatic APC, CTNNB1 or RNF43 PVs, that causes rapid progression to carcinoma." (PMID 36291559, 2022). "Furthermore, Rnf43 and Znrf3 transcripts decreased significantly in the Lef1-deleted adenoma cells concomitantly with decreased expression of Wnt antagonists." (PMID 34788095, 2021). "Thus, it has been proposed that downregulation of RNF43 occurs rather early during carcinogenesis and that it is important for the transition from adenoma to carcinoma." (PMID 31248166, 2019). "There is evidence that tumors with MSI develop from flat lesions via mutation in RNF43 (serrated adenoma pathway) rather than the adenoma to adenocarcinoma pathway, which is associated with gatekeeper mutations in the APC gene." (PMID 30001362, 2018).
adenoma (continued). "In traditional serrated adenomas, which are by nature dysplastic, are thought to have transitioned from hyperplastic polyps or sessile serrated lesions, and this transition coincides with the acquisition of WNT pathway alterations, such as RSPO fusions and RNF43 mutations." (PMID 32384699, 2020). "RNF43 mutations have been observed in BRAF-mutant sessile or traditional serrated adenomas, but not in their KRAS-mutant counterparts, suggesting that the alternate modalities of MEK–ERK pathway activation may determine the method by which the Wnt pathway is activated." (PMID 35975243, 2022). "We show that Lef1 is expressed in Wnt ligand–independent Apc-mutant adenomas, but not in Wnt ligand–dependent Rnf43;Znrf3-mutant intestine." (PMID 34788095, 2021). "By contrast, MMR-P adenomas had a higher frequency of APC and CTNNB1 somatic mutations, but no RNF43 somatic mutations." (PMID 33923068, 2021).